CDKN2A (cyclin dependent kinase inhibitor 2A)
Diseases named in the same sentence as CDKN2A in open-access papers (continued):
Sharing a sentence is not in itself a finding about the gene and the disease.
melanoma (continued). "The loss of CDKN2A heterozygosity is considered the first step in developing melanoma in patients with FAMMM syndrome." (PMID 35465855, 2022). "The efficacy of immunotherapy against melanoma and other cancers was examined in a larger group of patients carrying various CDKN2A major loss-of-function (LOF) mutations." (PMID 36291906, 2022). "Mutations in the CDKN2A gene have been observed in several types of cancers, such as melanoma-like, pancreatic, intestinal, prostate, and gastric lymphoma." (PMID 35330370, 2022). "Mutations of the CDKN2A carry a high risk of melanoma, together with CDK4, TERT, and POT1 gene mutations." (PMID 35465855, 2022). "Histopathologic characteristics and somatic mutations of melanomas in individuals with CDKN2A PVs are similar to those with sporadic melanoma." (PMID 35372037, 2022). "Mean age at melanoma diagnosis is earlier in CDKN2A mutation carriers than in the general population (mean of 35 years vs 59 years)." (PMID 35320498, 2022). "The effectiveness of immunotherapy in melanoma patients carrying the CDKN2A mutation was investigated." (PMID 36291906, 2022). "In melanoma cells, genetic mutations affecting the CDKN2A locus cause suppression of p16/INK4A, resulting in uncontrolled cell cycle progression." (PMID 36286442, 2022). "We chose B16F10 melanoma as they have a large deletion within the CDKN2A locus (encoding p16INK4A) and increased CDK4/6 activity." (PMID 35525274, 2022). "While the germline mutations of CDKN2A account for just 1–2% of melanoma cases in the general population, its prevalence increases with the number of primary melanomas diagnosed in a single patient and the presence of a familial history." (PMID 34442055, 2021). "Ras genes and CDKN2A were the earliest gene mutations identified in melanoma in the 1980s and 1990s." (PMID 34828357, 2021). "TERT promoter mutations and CDKN2A are also frequently found in these melanomas, and KIT mutations are found in a subset of cases." (PMID 34571969, 2021). "The CDKN2A mutated melanoma cells are expected to be more sensitive to RRM2 inhibitor cladribine that was in clinical development for multiple sclerosis and leukemia, as reported by SLKG." (PMID 33627666, 2021). "Cyclin-dependent kinase 2a (CDKN2A) was the first high-risk susceptibility gene identified in melanoma." (PMID 34680938, 2021). "The presence of the CDKN2A melanoma susceptibility has been observed also in patients with multiple primary melanoma (MPM)." (PMID 34440462, 2021). "Individuals identified to be carriers of the at-risk CDKN2A variant for melanoma (n = 15) reported higher distress, higher uncertainty, and lower positive feelings immediately after receiving their result than noncarriers." (PMID 34748551, 2021). "For instance, in people with two or more relatives affected by melanoma, there is a 25% probability of detecting a germline CDKN2A mutation." (PMID 34442055, 2021). "The mutation of the CDKN2A gene in the germline can result in a significant risk of developing melanoma or pancreatic cancer." (PMID 35004325, 2021). "Aberrant MYC (gain) and CDKN2A (loss or mutation) have been frequently detected in various human cancers, including melanoma." (PMID 34885165, 2021). "Germline mutations in CDKN2A, encoding the tumor suppressor p16, are responsible for a large proportion of familial melanoma cases and also increase risk of pancreatic cancer." (PMID 33823155, 2021). "CDKN2A is the major susceptible gene in multiple primary melanoma patients; it acts as a tumor suppressor gene, negatively regulating G1-S cell-cycle progression and promoting cellular senescence." (PMID 34356109, 2021).
melanoma (continued). "Less common melanoma susceptibly genes include CDKN2A/ARF, CDK4 (cyclin-dependent kinase 4), TERT, MITF (melanocyte inducing transcription factor), BAP1 (BRCA1 associated protein-1), and POT1 (protection of telomeres 1)." (PMID 34440462, 2021). "For each patient with multiple primary melanomas harboring a CDKN2A germline mutation, it is possible to find the same kind of dermoscopical pattern among their melanocytic tumors." (PMID 34440462, 2021). "Germline mutations of CDK4, albeit quite rare, predispose carriers to melanoma development to a similar extent to that observed in individuals harboring CDKN2A mutations." (PMID 34442055, 2021). "In cases where patients have first-degree relatives with a previous melanoma diagnosis, 20%-40% will carry a CDKN2A mutation." (PMID 34155457, 2021). "For example, activating mutations in KRAS/NRAS are frequently accompanied by loss of function of CDKN2A/B in melanoma, lung, pancreatic, and other cancers." (PMID 33769711, 2021). "The CDKN2A gene is the major high-penetrance familial melanoma predisposition gene, with germline mutations identified in 20%-40% of melanoma families." (PMID 34123788, 2021). "CDKN2A homozygous deletions, mutations and p14ARF histone de-acetylation are described in melanoma cell lines and tissues." (PMID 34639015, 2021). "Previous study has indicated that CDKN2A is a key mutation for melanoma while the effective treatment of such mutation type of melanoma is still lack." (PMID 33627666, 2021). "For example, the risk of developing melanoma in an 80-year-old individual with a family mutation of CDKN2A is increased by 58% in Europe, 76% in the US and 91% in Australia." (PMID 34442055, 2021). "Somatic impairment of the CDKN2A gene in melanoma can occur by genetic deletions, inactivated mutations, or promoter hypermethylation and leads to a decrease of the function of p16CDKN2A and/or p14CDKN2A proteins, with consequent loss of cell cycle control." (PMID 34571969, 2021). "A positive family history associates with intensifying risk of melanoma; approximately 10% of melanoma occurs in a familial setting with CDKN2A mutations." (PMID 34711012, 2021). "The results demonstrated that deletion of chromosome 15q, including B2M, caused loss of PTEN and cyclin-dependent kinase inhibitor 2A (CDKN2A) homozygous deletion was observed in the resistance to immunotherapy in melanoma patients." (PMID 34827646, 2021). "Germline mutations in CDKN2A are an established risk factor for the development of hereditary melanoma syndromes, and increase the risk of hereditary melanomas by at least 10-fold." (PMID 34831002, 2021). "In our study, we retrospectively collected data of patients with germline CDKN2A pathogenic variants who received targeted therapy for advanced melanoma across four European centers." (PMID 34069952, 2021). "Accordingly, a significant joint-effect of RHC variants (R163Q and D294H), considered either alone or in the presence of pigmentation and dysplastic nevi, influenced the penetrance of CDKN2A mutations in 20 French melanoma-prone families." (PMID 34356109, 2021). "Mutation of the CDKN2A gene at the germline level is the most frequent genetic alteration in patients with a strong familial history of melanoma." (PMID 34571969, 2021). "Families with CDKN2A germline mutations show an increased prevalence of other cancers beyond melanoma, including breast cancer." (PMID 34660619, 2021). "The cyclin-dependent kinase inhibitor 2A (CDKN2A) gene, located on 9p21.3, encodes two tumor suppressor proteins that are frequently mutated in human cancer, including melanoma." (PMID 34944843, 2021). "It appears, in fact, that in regions with higher incidence of melanoma there is a greater possibility of finding multiple family members with melanoma or multiple primary melanomas caused by reasons other than CDKN2A mutations." (PMID 34442055, 2021).
melanoma (continued). "The loss of the CDKN2A locus also cooperates with Cyclin D1 in promoting resistance to BRAF inhibitors in melanoma." (PMID 34066022, 2021). "Cancer susceptibility among germline variant carriers of CDKN2A extend beyond the well-known predisposition to melanoma and pancreatic cancer, potentially associated with a multitude of cancers." (PMID 33766116, 2021). "We observed that the expression profile from healthy keratinocyte-melanocyte co-culture of CDKN2A-mutated individuals was more similar to melanoma tumor expression than wild-type." (PMID 34660619, 2021). "In the case of inactivating germline mutations, CDKN2A is one of the DDR-related genes associated with inherited/familial predisposition for melanoma, glioblastoma multiforme and pancreatic cancer." (PMID 34454516, 2021). "The average age of diagnosis of melanoma in CDKN2A-mutated patients is between 30 and 40 years, whereas that of the general population is around 50 years." (PMID 34442055, 2021). "Somatic CDKN2A alterations are common driver events in melanoma, and are associated with tumor proliferation, increased risk of metastases and decreased OS." (PMID 34069952, 2021). "Since the loss of p16 (CDKN2A) expression has been associated with sensitivity to the CDK4/6 inhibitor palbociclib in melanoma cell lines and breast cancer patient, we further investigated p16 RNA and protein expression in metastatic lung lesion and PDX-mlung." (PMID 34885073, 2021). "In total, 45% of the melanomas tied to a genetic etiology are associated with a known germline mutation in CDKN2A or CDK4." (PMID 34638397, 2021). "In melanoma cell lines MITF amplification is commonly accompanied by CDKN2A inactivation and BRAF mutation." (PMID 33556121, 2021). "Loss of CDKN2A was also commonly found in BRAFi resistant melanomas and is linked to the MAPK pathway as an inhibitor of the downstream effectors cyclin D and cyclin-dependent kinase 4 (CDK4)." (PMID 34066966, 2021). "On the other hand, the loss of expression of the cell cycle inhibitor CDKN2A occurs in melanoma through different mechanisms including deletions, inactivating mutations and epigenetic silencing." (PMID 34066022, 2021). "For instance, in the FAMMM syndrome, which is characterized by the presence of multiple atypical and common nevi, both CDKN2A pathogenic variants and the nevus count affect the risk of melanoma in a synergistic manner." (PMID 34356093, 2021). "RB pathway activity has also been diminished in melanoma due to inactivating mutations and the epigenetic silencing of CDKN2A." (PMID 34066022, 2021). "Approximately 40% of familial cases can be attributed to high penetrance melanoma susceptibility genes such as CDKN2A, CDK4 and BAP1." (PMID 34572747, 2021). "Fittingly, those with at least one melanoma and with either a personal or familial history of pancreatic cancer have a 9.7% chance of harboring a mutation in CDKN2A." (PMID 34442055, 2021). "An estimated 5–10% of all melanomas are hereditary, and of those, up to 40% are explained by germline mutations in cyclin-dependent kinase inhibitor 2a (CDKN2A)." (PMID 34356109, 2021). "Heterozygous loss of CDKN2A is sufficient to confer a 67% lifetime risk of melanoma and it is associated with high inherited risk in melanoma prone families." (PMID 34356109, 2021). "The CDKN2A mutation can also be found in around 10% of sporadic patients with multiple primary melanomas." (PMID 34440462, 2021). "CDKN2A is one of these predisposing genes which have been estimated to be involved in germ line mutation in approximately 5-10% of familial melanoma cases." (PMID 34711012, 2021). "Mutations in KIT, BRAF, NRAS and cyclin-dependent kinase inhibitor 2A (CDKN2A) also participate in melanoma progression as do mutations that lead to excessive PI3K-Akt signaling." (PMID 34769150, 2021).
melanoma (continued). "CDKN2A is a melanoma susceptibility gene mutated in 20–50% of familial melanoma cases and 2–3% of sporadic melanomas." (PMID 34944799, 2021). "Our group identified four familial melanoma/pancreatic cancer kindreds segregating a rare germline missense variant, CDKN2A (47T>G), that encodes the variant protein p16-L16R." (PMID 33823155, 2021). "Other contributors that promote the uncontrolled proliferative capacity of melanoma cells include mutations in the cell cycle regulating genes, CDKN2A and CDK4, as well as promoter region of Telomerase Reverse Transcriptase (TERT)." (PMID 34359771, 2021). "CDKN2A is the main predisposing gene also for melanoma and it contributes to the genetic architecture of melanoma as mutations are found in about 30% of patients in rare families of three or more affected individuals." (PMID 34503195, 2021). "Another study had reported the known germline mutation of CDKN2A (322G>A: Asp108Asn) in Australian population and its role in melanoma predisposition." (PMID 34711012, 2021). "Surveys were conducted with 55 participants who were part of a cohort of people with pancreatic cancer who were tested for variants in CDKN2A for melanoma risk, explored the outcomes from returning SSR to biobank participants." (PMID 34748551, 2021). "Concerning gastric cancer, there are some reports for the association of this cancer in the family with melanoma and CDKN2A gene mutation." (PMID 34711012, 2021). "Familial melanoma studies identified the CDKN2A locus, which encodes for protein p16INK4a and p19ARF, and their loss of expression is common in melanoma." (PMID 34066966, 2021). "MC1R variants have been shown to increase the penetrance of CDKN2A mutations (observed risk over time for a mutation carrier), doubling the risk of melanoma development." (PMID 34356109, 2021). "Pathogenic variants in CDKN2A, a major tumor suppressor gene, account for 35% to 40% of familial melanomas." (PMID 33509032, 2021). "In recent work, the combination of CDK4 and MDM2 inhibitors demonstrated significant preclinical activity, and this combination was effective in melanoma models with genetic loss of CDKN2A." (PMID 33076392, 2020). "Germline CDKN2A mutations have been found in about 20–40% of melanoma-prone families (with ≥3 melanoma cases), but in only 0.2–3% of non-familial melanoma cases." (PMID 33050356, 2020). "A germline splice site mutation removing exon 2 of CDKN2A was identified in a family with melanoma and multiple dysplastic nevi." (PMID 33076392, 2020). "Mutations in the CDKN2A gene are the most common alteration in hereditary melanoma, with presence in 40% of families with strong family history." (PMID 32429485, 2020). "The genetic counseling report to the melanoma patient stated that the CDKN2A variant was ‘likely pathogenic’ and the disease was defined as ‘likely hereditary melanoma’." (PMID 32760473, 2020). "Around 10% of people with melanoma have a family history of the disease, and CDKN2A is the most highly penetrant susceptibility gene in familial melanoma." (PMID 32987645, 2020). "A GenoMEL study that screened for CDKN2A mutations in Australian, European, and North American families reported increased mutation frequency in families with melanoma and pancreatic cancer." (PMID 33076392, 2020). "In melanoma, loss of function CDKN2A alterations have been identified in approximately 50% of primary melanomas, in over 75% of metastatic melanomas, and in the germline of 40% of families with a predisposition to cutaneous melanoma." (PMID 33076392, 2020).
melanoma (continued). "The penetrance of germline CDKN2A mutations for melanoma also varies according to geographical locations, with penetrance increasing with higher baseline melanoma incidence rates." (PMID 33076392, 2020). "Germline alterations in the CDKN2A locus have also been identified in approximately 40% of high-risk melanoma families with three or more melanoma cases." (PMID 33076392, 2020). "miRNA-204-5p, known as a tumour suppressor gene in melanoma, was associated with the CDKN2A pathway and NRAS gene and contributed to BRAF inhibitor resistance.." (PMID 32993558, 2020). "A total of 9 patients (3.4%) carried mutations in high-to-moderate melanoma risk genes (CDKN2A, POT1, ACD) and 22 (8.3%) patients in other cancer syndrome genes (NBN, BRCA1/2, CHEK2, ATM, WRN, RB1)." (PMID 33050356, 2020). "The most common high-risk predisposing gene for cutaneous melanoma (subsequently melanoma) is cyclin dependent kinase inhibitor 2A (CDKN2A)." (PMID 32760473, 2020). "A first clue to identifying tumor-driving mutations in melanoma came from the existence of germline mutations in the CDK inhibitor gene CDKN2A (also known as p16)." (PMID 34589668, 2020). "MC1R variants have furthermore been shown to increase the melanoma risk in families possessing cyclin-dependent kinase inhibitor 2A (CDKN2A) mutations." (PMID 32605315, 2020). "The loss of the CDKN2A locus is the most common acquired genetic change in precursor lesions, including in situ melanomas." (PMID 32850962, 2020). "Melanoma-associated CDKN2A missense mutations commonly diminish the capacity of p16INK4a to bind and inhibit CDK4/6." (PMID 33076392, 2020). "Until now, it was not possible to identify specific gene mutations, like the loss of CDKN2A that promote the development of melanoma metastases in humans." (PMID 32165639, 2020). "Four out of six CDKN2A mutation carriers developed >1 melanoma (3 patients) or other cancer (1 patient); all six carriers had a positive family cancer history and five of them had at least one relative with melanoma." (PMID 33050356, 2020). "Histological analysis of CDKN2A-mutated familial melanomas revealed a greater association with the superficial spreading subtype as compared with CDKN2A-wild type familial melanomas." (PMID 32429485, 2020). "Mutations in CDKN2A are detected in 10–40% of familial melanoma cases, with CDK4 also an established melanoma predisposition gene." (PMID 32987645, 2020). "Familial history is also one of the risk factors for developing melanoma, with cyclin-dependent kinase inhibitor 2A (CDKN2A) and cyclin-dependent kinase 4 (CDK4) being the most common heritable mutations." (PMID 32092958, 2020). "Those with the CDKN2A mutation have been shown to develop multiple melanomas and significantly more dysplastic nevi, including presentations consistent with dysplastic nevus syndrome." (PMID 32429485, 2020). "These CDKN2A germline mutations are associated with a 65-fold increase in the risk of melanoma development." (PMID 33076392, 2020). "Loss of function alterations affecting the CDKN2A locus have been identified in the germline of multiple-case melanoma kindreds around the world." (PMID 33076392, 2020). "Loss of the cyclin‐dependent kinase inhibitor 2A (CDKN2A) tumour suppressor gene is the most common acquired genetic change in invasive melanoma." (PMID 32374893, 2020). "In a recent report of a multi-gene panel screening of Dutch non-CDKN2A/CDK4 melanoma families, 9 rare pathogenic variants of OCA2 were found." (PMID 32966289, 2020).